SNORD70B (small nucleolar RNA, C/D box 70B)
Gene: Small nucleolar RNA gene on chromosome 2 (202,278,108 to 202,278,192, forward strand). Ensembl gene ENSG00000212309.
Gene Ontology:
Biological process: RNA processing
Cellular component: nucleolus
Homologues: Orthologues: macaque SNORD70B (99% identical), mouse Gm26293 (95% identical), pig SNORD70B (95% identical), rabbit SNORD70B (95% identical), guinea pig SNORD70B (93% identical), rat Snord70b (92% identical), zebrafish SNORD70B (59% identical). Paralogues in human: SNORD70 (91% identical).